EGFR (epidermal growth factor receptor)
Diseases named in the same sentence as EGFR in open-access papers (continued):
Sharing a sentence is not in itself a finding about the gene and the disease.
metastatic colorectal cancer (continued). "Life-prolonging systemic therapies, e.g., chemotherapies with or without molecular targeted agents such as anti-vascular endothelial growth factor (VEGF) or anti-epidermal growth factor receptor (EGFR) agents, are important for unresectable metastatic colorectal cancer (mCRC)." (PMID 28007025, 2016). "Cetuximab, a human/mouse chimeric monoclonal antibody against the epidermal growth factor receptor (EGFR), is used as a single agent and in combination with chemotherapy or radiation therapy in metastatic colorectal cancer and locally advanced or metastatic head and neck squamous cell cancer." (PMID 27378078, 2016). "The anti-EGFR monoclonal antibodies cetuximab (ErbituxTM, Bristol Myers Squibb and Merck KGaA) and panitumumab (VectibixTM, Amgen) are approved for the treatment of metastatic colorectal cancer (mCRC)." (PMID 27683110, 2016). "Additionally, USD 604 million in annual savings would be realized if genetic tests limiting anti-epidermal growth factor receptor (EGFR) therapy to metastatic colorectal cancer patients with wild-type KRAS tumors are carried out." (PMID 26425215, 2015). "Targeted therapy of metastatic colorectal cancer (mCRC) with monoclonal antibody anti-epidermal growth factor receptor (EGFR) agents, such as cetuximab (CTX) or panitumumab, is the treatment strategy of choice in patients characterised by a wild-type (wt) RAS gene status." (PMID 25663927, 2015). "Treatment options for patients with metastatic colorectal cancer (mCRC) have changed considerably in recent years with the introduction of antiepidermal growth factor receptor (EGFR) therapies targeting EGFR transduction cascade, which is one of the leading oncogenic pathways used by tumoral cells." (PMID 25983749, 2015). "Cancer-related immune antigens in the tumor microenvironment could represent an obstacle to agents targeting EGFR “cetuximab” or VEGF “bevacizumab” in metastatic colorectal cancer (mCRC) patients." (PMID 26427914, 2015). "The idea of personalized medicine was introduced to the treatment of metastatic colorectal cancer (mCRC) when KRAS codon 12/13 mutations were identified as negative predictors of anti-EGFR-antibody (EGFR-mAB) treatment." (PMID 24816724, 2014). "Molecular profiling for somatic mutations that predict absence of response to anti-EGFR therapy has become standard practice in the treatment of metastatic colorectal cancer; however, the quantity and type of tissue available for testing is frequently limited." (PMID 25164765, 2014). "However, only about half of metastatic colorectal cancer patients with wild-type KRAS tumors respond to anti-EGFR treatment 9, indicating a need for additional biomarkers of treatment response." (PMID 24890702, 2014). "Since the KRAS mutation is not responsible for all metastatic colorectal cancer (mCRC) patients with resistance to anti-epidermal growth factor receptor (EGFR) monoclonal antibody (MoAb) therapy, new predictive and prognostic factors are actively being sought." (PMID 24500024, 2014). "Only approximately 10 % of genetically unselected patients with chemorefractory metastatic colorectal cancer experience tumor regression when treated with the anti-epidermal growth factor receptor (EGFR) antibodies cetuximab or panitumumab (“primary” or “de novo” resistance)." (PMID 24811491, 2014). "Loss of phosphatase and tensin homologue (PTEN) function evaluated by loss of PTEN protein expression on immunohistochemistry (IHC) has been reported as both prognostic in metastatic colorectal cancer and predictive of response to anti-EGFR monoclonal antibodies although results remain uncertain." (PMID 24564252, 2014). "Characteristics of anti-EGFR treated KRAS wild type metastatic colorectal cancer patients." (PMID 24940619, 2014). "However, even after restricting to studies of metastatic colorectal cancer patients treated with anti-EGFR therapies, heterogeneity remained, suggesting a possible important role of concomitant treatments." (PMID 24890702, 2014).
metastatic colorectal cancer (continued). "Contrary to our efforts to reduce between-study heterogeneity through subgroup analysis restricted to metastatic colorectal cancer patients with metastatic disease treated with anti-EGFR therapies, a high degree of heterogeneity remained (P = 0.01, I2 = 73.3%)." (PMID 24890702, 2014). "Interestingly, almost all studies addressing EGFR-inhibitor-induced skin rash done in patients with metastatic colorectal cancer suggest that its severity is a suitable surrogate marker for efficacy of anti-EGFR therapy." (PMID 23855804, 2013). "Cetuximab, Immunoglobulin, Rituxan and Thymoglobulin are immune-related drugs encoded by FCGR3A and CD4 genes in which Cetuximab is an epidermal growth factor receptor (EGFR) inhibitor used for the treatment of metastatic colorectal cancer and head and neck cancer." (PMID 24564241, 2013). "Epidermal growth factor receptor (EGFR) monoclonal antibody was approved for treatment of metastatic colorectal cancer patients without KRAS mutations." (PMID 23874486, 2013). "The association between KRAS mutation and the lack of benefit of anti-EGFR monoclonal antibodies, such as cetuximab and panitumumab, in metastatic colorectal cancer has been established." (PMID 24179496, 2013). "The anti-EGFR mAbs have been proven to be effective in metastatic colorectal cancer." (PMID 23441167, 2013). "An international interlaboratory reproducibility ring study [as that performed for EGFR FISH analysis in metastatic colorectal cancer (CRC) patients] is missing and has to be performed in order to ascertain the difficulties and the discrepancies in PTEN evaluations in different laboratories." (PMID 24475377, 2013). "In metastatic colorectal cancer, objective response to anti-EGFR antibody therapy can be expected in a third of unselected patients, and conversely, tumor KRAS mutations may be found in almost a third of responders." (PMID 23226389, 2012). "At present, standard first-line treatment for patients with metastatic colorectal cancer (mCRC) includes combination chemotherapy in conjunction with either an anti-epidermal growth factor receptor (EGFR) agent such as cetuximab or panitumumab, or an antiangiogenic agent, such as bevacizumab." (PMID 23174912, 2012). "Novel strategies that target the epidermal growth factor receptor (EGFR) have led to the clinical development of monoclonal antibodies, which treat metastatic colorectal cancer (mCRC) but only subgroups of patients with increased wild type KRAS and EGFR gene copy, respond to these agents." (PMID 23144978, 2012). "Several retrospective studies have indicated that the mutation status of BRAF may also be predictive of response to anti-EGFR therapies in patients with metastatic colorectal cancer." (PMID 23202889, 2012). "Although tumour growth in responsive patients may be closely linked to an increase in EGFR/CEP7 ratio, the literature in other tumour entities, especially in metastatic colorectal cancer demonstrates the experimental difficulties in finding a valid cut-off." (PMID 22152101, 2011). "EGFR-targeted monoclonal antibodies (cetuximab and panitumumab) have been found to significantly improve disease response and are currently being used in treatment of metastatic colorectal cancer." (PMID 24212832, 2011). "Tumor budding may also prove useful in prediction of response to anti-epidermal growth factor receptor based therapies (cetuximab or panitumumab) in metastatic colorectal cancer patients (along with K-RAS)." (PMID 24212832, 2011). "The aim of the present study was to investigate the clinical value of triple KRAS, BRAF and PIK3CA mutational testing by commercially available kits combined with immunohistochemical testing of EGFR and PTEN loss in a material of patients with metastatic colorectal cancer." (PMID 21439039, 2011).
metastatic colorectal cancer (continued). "The high frequency of KRAS mutations in serrated adenocarcinomas also indicates that most serrated adenocarcinomas are natively insensitive to epidermal growth factor receptor-blocking therapies, which are increasingly being used to treat metastatic colorectal cancer." (PMID 21457162, 2011). "Biomarker driven anti-EGFR therapy is now established in metastatic colorectal cancer with the discovery that tumours with mutated KRAS do not respond to anti-EGFR therapy." (PMID 24281034, 2010). "Several studies demonstrated that epidermal growth factor receptor (EGFR) gene copy number (GCN) correlates to the response to tyrosine kinase inhibitors in non small cell lung cancer (NSCLC) and to anti-EGFR monoclonal antibodies (MoAbs) in metastatic colorectal cancer (CRC)." (PMID 20843314, 2010). "Cetuximab and panitumumab efficacy in metastatic colorectal cancer (mCRC) may be influenced by EGFR gene status and/or deregulation of its downstream signalling proteins detected in primary tumour." (PMID 19293803, 2009). "Novel biological agents, such as cetuximab (C225, Erbitux®), a recombinant human/mouse monoclonal antibody against epidermal growth factor receptors (EGFR), have recently been shown to improve the clinical benefit for patients with metastatic colorectal cancer." (PMID 18182978, 2008). "The impact of KRAS mutations on cetuximab sensitivity in epidermal growth factor receptor fluorescence in situ hybridisation-positive (EGFR FISH+) metastatic colorectal cancer patients (mCRC) has not been previously investigated." (PMID 18577988, 2008). "Background/Objectives: In metastatic colorectal cancer (mCRC), liquid biopsy has enabled the identification of “neo-RAS-Wild-Type (WT)”, a transient phase characterized by the disappearance of RAS mutations, with significant clinical implications for re-sensitization to EGFR blockade." (PMID 40227564, 2025). "While anti-EGFR therapy was associated with a higher likelihood of tumor fibrosis ≥40% compared to anti-VEGF therapy, this did not result in improved overall survival among patients undergoing resection of hepatic M1 metastases from metastatic colorectal cancer (mCRC)." (PMID 40507350, 2025). "The recommended treatment for individuals with metastatic colorectal cancer (mCRC) involves chemotherapy protocols that include fluorouracil, oxaliplatin, and/or irinotecan, together with medications that target angiogenesis (bevacizumab) or the epidermal growth factor receptor (cetuximab)." (PMID 39100666, 2024). "The clinical utility of LP has been demonstrated for the detection of epidermal growth factor receptor (EGFR) mutations in non-small cell lung cancer (NSCLC) patients or for the detection of KRAS proto-oncogene, GTPase (KRAS) mutations in patients suffering from metastatic colorectal cancer (CRC)." (PMID 35328301, 2022). "This is of particular clinical relevance when we consider that metastatic colorectal cancer patients who are potential candidates for a rechallenge with anti-EGFR may also be eligible, at the same time, for other therapeutic options with higher level of evidence." (PMID 35530345, 2022). "Patients with metastatic colorectal cancer are often eligible for palliative chemotherapy, consisting of a combination of 5-fluorouracil, oxaliplatin, irinotecan, antibodies against epidermal growth factor receptor (EGFR) and/or vascular endothelial growth factor (VEGF), and regorafenib." (PMID 35035479, 2022).
metastatic colorectal cancer (continued). "Other examples include epidermal growth factor receptor (EGFR) immunohistochemistry and KRAS proto-oncogene (KRAS) exon 2 mutation tests for determining the likelihood of treatment response to cetuximab or panitumumab treatment in metastatic colorectal cancer (CRC)." (PMID 34065872, 2021). "Cell 2 presented a good initial response against EGFR inhibitors, but the occurrence of the two PIK3CA pathogenic variants could be translated into the later acquisition of resistance to treatment, as described in metastatic colorectal cancer." (PMID 33917394, 2021). "For example, patients with metastatic colorectal cancer harboring mutations in exon 2 of K-ras did not benefit from anti-epidermal growth factor receptor (EGFR) therapy, only those patients with wild-type ras genes could benefit from such treatment." (PMID 33765976, 2021). "For example, a combination therapy consisting of anti-EGFR monoclonal antibodies and autophagy inhibitors would represent a multi-pronged approach that could be developed into an active therapeutic strategy in metastatic colorectal cancer patients." (PMID 31896739, 2020). "Monoclonal antibodies (MoAbs) against EGFR, such as cetuximab and panitumumab, have been developed and are able, by binding to EGFR extracellular domain, to prevent its activation, demonstrating high efficacy in metastatic colorectal cancer (mCRC), but only in a subgroup of patients." (PMID 33233823, 2020). "In patients with metastatic colorectal cancer (mCRC), analysis of mutations in KRAS codons 12 and 13 is commonly performed before starting treatment with cetuximab or panitumumab, which are antibody-based therapeutic medicines that target the epidermal growth factor receptor (EGFR)." (PMID 32059456, 2020). "Regorafenib is an oral multikinase inhibitor for metastatic colorectal cancer (mCRC) previously treated with fluoropyrimidines, irinotecan, oxaliplatin, monoclonal antibodies targeting vascular endothelial growth factor, and monoclonal antibodies targeting epidermal growth factor receptor." (PMID 31856912, 2019). "Given this evidence, the KRAS mutation testing is approved by food and drug administration (FDA) for treatment of KRAS mutation-negative (wild-type), EGFR-expressing metastatic colorectal cancer, and is required by European medicines agency (EMA) before the initiation of anti-EGFR therapy." (PMID 30406144, 2018). "Importantly, retrospective studies including small number of selected patients with metastatic colorectal cancer (mCRC) patients treated with anti-EGFR therapy have shown LqB capable to detect the acquired clonal mutations in RAS genes leading to therapy resistance." (PMID 27852040, 2017). "In almost 60% metastatic colorectal cancer (mCRC) patients, K-RAS and N-RAS are mutated and mutations are considered a predictor of poor response to anti-EGFR monoclonal antibodies (mABs), such as cetuximab or panitumumab, while patients with wild-type RAS benefit from EGFR targeted treatment." (PMID 27304055, 2016). "Furthermore, analysis of tissue samples from 130 participants in the IMC-0144 trial of cetuximab in patients with metastatic colorectal cancer showed that polymorphisms in PTGS2, which encodes COX-2, and EGFR predicted progression-free survival independently of K-RAS mutation status." (PMID 27074568, 2016). "In addition, it is necessary to verify whether the subtypes or site of metastatic colorectal cancer play a role in response to anti-EGFR-TK therapy, like cetuximab." (PMID 25950441, 2015). "However, the potential to predict telomere length based on molecular stratification of tumors is of clinical importance: longer telomeres were shown to predict the sensitivity of metastatic colorectal cancer to cetuximab, an anti-epidermal growth factor receptor (EGFR) drug." (PMID 25871393, 2015).
metastatic colorectal cancer (continued). "Previous studies showed that the benefits of the anti-EGFR mAb cetuximab among patients with metastatic colorectal cancer are limited to those patients who have colorectal tumor tissues with wild-type KRAS genes, and KRAS genes with mutations are essentially insensitive to EGFR inhibitors." (PMID 24884535, 2014). "The overall survival (OS) time of patients with metastatic colorectal cancer (CRC) has increased owing to novel therapeutic strategies combining chemotherapy with monoclonal antibodies against vascular endothelial growth factor (VEGF) or epidermal growth factor receptor (EGFR)." (PMID 20924372, 2010). "Large phase III randomised studies in metastatic colorectal cancer have demonstrated either response rate or time to progression advantages using monoclonal antibodies, such as cetuximab, directed specifically against the epidermal growth factor receptor (EGFR)." (PMID 18253119, 2008). "Oxaliplatin and irinotecan, when combined with fluorouracil, are used as doublet regimens in the first-line treatment of metastatic colorectal cancer, often in combination with anti-EGFR (epidermal growth factor receptor) or anti-VEGF agents." (PMID 41301066, 2025). "Cetuximab, an EGFR-targeting monoclonal antibody, provides beneficial yet limited clinical improvement in KRAS wild-type metastatic colorectal cancer (mCRC)." (PMID 41214390, 2025). "For example, cetuximab is an anti-epidermal growth factor receptor (EGFR) monoclonal antibody approved for treating head and neck squamous cell carcinoma (HNSCC) and metastatic colorectal cancer." (PMID 41019287, 2025). "In metastatic colorectal cancer (mCRC), RAS testing is a critical part of treatment planning and is required before starting anti-EGFR therapies." (PMID 40227564, 2025). "Cetuximab is a treatment widely used to treat advanced, metastatic colorectal cancer (CRC), and it works by blocking epidermal growth factor receptor signaling." (PMID 39001533, 2024). "An anti-epidermal growth factor receptor (EGFR) mAb, cetuximab, was approved by the FDA for metastatic colorectal cancer in 2004 and head and neck squamous cell carcinomas (HNSCCs) in 2006." (PMID 39594582, 2024). "Therapeutic anti-EGFR moAbs (cetuximab and panitumumab) remain the mainstay of targeted therapy in RAS/BRAF wild-type metastatic colorectal cancer." (PMID 38711991, 2024). "EGFR‐targeted monoclonal antibodies, such as cetuximab, are used to treat KRAS‐wild type metastatic colorectal cancer, but eventually, resistance to this therapy emerges." (PMID 38887984, 2024). "The combination of the anti-EGFR antibody cetuximab with irinotecan or the FOLFIRI regimen has improved treatment outcomes in RAS and BRAF wild-type metastatic colorectal cancers." (PMID 39033209, 2024). "Of all cancer types, the use of targeted therapies was greatest in metastatic colorectal cancers, where EGFR (epidermal growth factor receptor) inhibitors (e.g., cetuximab) and anti-angiogenic agents (e.g., bevacizumab) are commonly used." (PMID 36831362, 2023). "The efficacy of cetuximab against metastatic colorectal cancer was demonstrated in the BOND study, suggesting that targeting the EGFR pathway is key to overcoming chemotherapy resistance." (PMID 37686423, 2023). "Causing infusion reactions in up to 25% of patients, cetuximab is a human/mouse chimeric antibody that targets the epidermal growth factor receptor EGFR, used in the management of metastatic KRAS wild-type metastatic colorectal cancer and head and neck tumors." (PMID 36835299, 2023). "Another EGFR antagonist, panitumumab, has also been approved by the FDA for wild-type RAS metastatic colorectal cancer in combination with FOLFOX as a first-line treatment and as a monotherapy after chemotherapy-derived disease progression." (PMID 37686423, 2023).